RMDN3 (regulator of microtubule dynamics 3)
Description:
Involved in cellular calcium homeostasis regulation. May participate in differentiation and apoptosis of keratinocytes. Overexpression induces apoptosis.
Synonyms: RMD-3; FAM82A2; FAM82C; PTPIP51; FLJ10579; RMD3
Tractability: Small molecule: a structure with a bound ligand is known. Antibody: UniProt predicts a signal peptide or a membrane-spanning region. PROTAC: ubiquitination databases record sites on it; its protein half-life has been measured.
Gene: Protein-coding gene on chromosome 15 (40,733,696 to 40,755,851, reverse strand). Ensembl gene ENSG00000137824.
Subcellular location: Mitochondrion outer membrane; Cytoplasm; Nucleus; Cytoplasm, cytoskeleton, spindle; Cytoplasm, cytoskeleton, spindle pole
Subcellular location (Human Protein Atlas): Mitochondria; Cytokinetic bridge
Gene Ontology:
Molecular function: microtubule binding; protein binding
Biological process: intracellular calcium ion homeostasis
Cellular component: cytoplasm; intercellular bridge; mitochondrial outer membrane; mitochondrion; mitotic spindle pole; nucleus; organelle membrane contact site; spindle microtubule; glutamatergic synapse; postsynapse; presynapse; spindle; spindle pole
Genetic constraint (gnomAD): Loss-of-function variants: 37 observed, 60.67 expected, observed/expected ratio (o/e) 0.61, 90% interval 0.47 to 0.8. The upper end of that interval is the gene's LOEUF score, 0.8, which puts it in group 3 of 6, group 1 being the genes least tolerant of losing a copy. Missense variants: 535 observed, 589.38 expected, observed/expected ratio (o/e) 0.91, 90% interval 0.85 to 0.98. Synonymous variants: 240 observed, 237.59 expected, observed/expected ratio (o/e) 1.01, 90% interval 0.91 to 1.12.
Homologues: Orthologues: chimpanzee RMDN3 (100% identical), macaque RMDN3 (97% identical), dog RMDN3 (89% identical), pig RMDN3 (86% identical), rat Rmdn3 (86% identical), rabbit RMDN3 (85% identical), mouse Rmdn3 (85% identical), guinea pig RMDN3 (83% identical), tropical clawed frog rmdn3 (53% identical), zebrafish rmdn3 (41% identical), Caenorhabditis elegans rmd-2 (20% identical), Caenorhabditis elegans C16C8.18 (14% identical), and 4 more. Paralogues in human: RMDN2 (31% identical), RMDN1 (20% identical), TEX10 (19% identical).
Diseases named in the same sentence as RMDN3 in open-access papers:
RMDN3 is named in the same sentence as 43 diseases in open-access papers, as found by Europe PMC text mining. Sharing a sentence is not in itself a finding about the gene and the disease. The quoted sentences say what the papers report.
cancer (9 papers, 2017 to 2023). A tumor composed of atypical neoplastic, often pleomorphic cells that invade other tissues. "The second apoptotic-related protein, RMDN3, also known as PTPIP51, is highly expressed in several cancers and regulates and interconnects with central oncogenic signaling pathways." (PMID 32728020, 2020).
infection (2 papers, 2022 to 2024). The state of being infected such as from the introduction of a foreign agent such as serum, vaccine, antigenic substance or organism. "PLA between VAPB and RMDN3 antibodies revealed an increased number of punctate PLA signals as the infection proceeded." (PMID 38620036, 2024).
RMDN3 also shares sentences with these, for which no sentence is quoted: amyotrophic lateral sclerosis (17 papers); Parkinson disease (13); neurodegenerative disease (11); Alzheimer disease (7); frontotemporal dementia (7); breast carcinoma (5); tumor (5); glioblastoma (4); acute myeloid leukemia (3); ischemic heart disease (3); dementia (2); ovarian carcinoma (2); atherosclerosis (1); breast adenocarcinoma (1); cardiac ischemia (1); cerebral infarction (1); Cerebral ischemia (1); cystic fibrosis (1); diabetic nephropathy (1); dysplastic nevi (1); epilepsy (1); fibrosis (1); glioma (1); HCMV infection (1); heart diseases (1); hereditary spastic paraplegia (1); infarction (1); Insulin resistance (1); ischemia (1); ischemic stroke (1).
A further 11 diseases each share a sentence with RMDN3 in 1 paper.